EIF4EBP3 (eukaryotic translation initiation factor 4E binding protein 3)
Description:
Repressor of translation initiation that regulates EIF4E activity by preventing its assembly into the eIF4F complex: the hypophosphorylated form competes with EIF4G1/EIF4G3 and strongly binds to EIF4E, leading to repression of translation. In contrast, the hyperphosphorylated form dissociates from EIF4E, allowing interaction between EIF4G1/EIF4G3 and EIF4E, leading to initiation of translation (By similarity). Inhibits EIF4E-mediated mRNA nuclear export.
Synonyms: 4E-BP3; 4EBP3
Tractability: PROTAC: ubiquitination databases record sites on it.
Gene: Protein-coding gene on chromosome 5 (140,547,662 to 140,549,576, forward strand). Ensembl gene ENSG00000243056.
Subcellular location: Cytoplasm; Nucleus
Gene Ontology:
Molecular function: protein binding; eukaryotic initiation factor 4E binding; translation repressor activity
Biological process: negative regulation of translational initiation
Cellular component: cytoplasm; membrane; nucleus; eukaryotic translation initiation factor 4F complex
Genetic constraint (gnomAD): Loss-of-function variants: 11 observed, 11.28 expected, observed/expected ratio (o/e) 0.97, 90% interval 0.61 to 1.59. The upper end of that interval is the gene's LOEUF score, 1.59, which puts it in group 6 of 6, group 1 being the genes least tolerant of losing a copy. Missense variants: 136 observed, 129.77 expected, observed/expected ratio (o/e) 1.05, 90% interval 0.91 to 1.21. Synonymous variants: 43 observed, 51.35 expected, observed/expected ratio (o/e) 0.84, 90% interval 0.65 to 1.08.
Homologues: Orthologues: dog EIF4EBP3 (98% identical), pig EIF4EBP3 (92% identical), guinea pig EIF4EBP3 (89% identical), rat Ankhd1 (88% identical), mouse Eif4ebp3 (87% identical), rabbit EIF4EBP3 (84% identical), zebrafish eif4ebp3l (67% identical), zebrafish eif4ebp3 (53% identical), Drosophila melanogaster Thor (39% identical). Paralogues in human: EIF4EBP2 (61% identical), EIF4EBP1 (57% identical).
Diseases named in the same sentence as EIF4EBP3 in open-access papers:
EIF4EBP3 is named in the same sentence as 10 diseases in open-access papers, as found by Europe PMC text mining. Sharing a sentence is not in itself a finding about the gene and the disease. The quoted sentences say what the papers report.
hepatocellular carcinoma (2 papers, 2016 to 2020). A malignant tumor that arises from hepatocytes. "A study in human cervical squamous carcinoma reported that miR-22-3p causes inhibition of cell apoptosis by targeting the eIF4EBP3 gene and suppresses cell proliferation in hepatocellular carcinoma and arterial smooth muscle by regulating SP1 and HMGB1, respectively." (PMID 32411089, 2020).
thyroid cancer (1 paper, 2021). "Here, we found a significant upregulation of EIF4EBP3 in cells treated with SS, and further functional experiments revealed that knocking down EIF4EBP3 mitigated the effect of SS in thyroid cancer." (PMID 34094961, 2021). "An mTOR signaling repressor gene, EIF4EBP3, was found to be involved in the anticancer effect of selenite in thyroid cancer." (PMID 34094961, 2021).
cancer (5 papers, 2009 to 2023). A tumor composed of atypical neoplastic, often pleomorphic cells that invade other tissues. "Consistent with our findings, a previous study reported that inhibition of mTOR by rapamycin upregulated EIF4EBP3 and induced cancer cell death." (PMID 34094961, 2021). "CRISPR/Cas9-mediated EIF4EBP3 gene disruption in human cancer cells mitigated the inhibition of translation and proliferation caused by prolonged treatment with mTOR inhibitors." (PMID 27319316, 2016). "It is possible that DNA methylation of the EIF4EBP3 gene also occurs in different cancers." (PMID 27319316, 2016). "The target of miR-22-3p is known as eIF4E-binding protein 3 (eIF4EBP3), a component of the PI3K/AKT pathway, which plays an important role in tumorigenesis and metastasis of many cancers." (PMID 35628433, 2022).
EIF4EBP3 also shares sentences with these, for which no sentence is quoted: Tumor (3 papers); breast carcinoma (2); leukemia (1); lymph node metastasis (1); myocarditis (1); pancreatic cancer (1); viral infection (1).